SLC39A14 (solute carrier family 39 member 14)
Diseases named in the same sentence as SLC39A14 in open-access papers (continued):
Sharing a sentence is not in itself a finding about the gene and the disease.
tumor (26 papers, 2015 to 2025). "These indicate the critical role of SLC39A14 in ferroptosis and regulation of tumor immune microenvironment." (PMID 38602575, 2024). "The results showed that SLC39A14 had an important correlation with the cGMP-PKG pathway.Multiple studies have shown that the cGMP-PKG pathway promotes tumor progression." (PMID 37978473, 2023). "Silencing SLC39A14 inhibits ferroptosis and tumor progression, potentially involving the regulation of the cGMP-PKG signaling pathway." (PMID 37978473, 2023). "HE results showed that SAS combined with silencing of SLC39A14 significantly reduced tumor malignancy." (PMID 37978473, 2023). "In vivo experiments further confirmed that the knockdown of SLC39A14 inhibited tumor growth by promoting ferroptosis." (PMID 37978473, 2023). "We found a cohort of genes that were nonspecific and had broad expression in other cell types in both normal and tumor contexts, including SLC39A14 and DUSP10." (PMID 35687691, 2022). "Then, the effects of circ_000829, SRSF1, and SLC39A14 on cell cycle distribution and proliferation in vitro and on tumor growth in vivo were evaluated in RCC cells." (PMID 36062189, 2022). "In contrast, SLC39A14 was expressed lower in tumor sample, and higher expression of which indicated a favorable OS in patients with BC, which suggested different role of SLC39A14 in BC." (PMID 32744318, 2020). "In addition, SLC39A14 supports tumor growth and inhibits ferroptosis by activating the cGMP-PKG pathway." (PMID 41583444, 2025). "Given the association between SLC39A14 and ATP13A2 and the similarities in immune and prognostic profiles, we hypothesize that ATP13A2 may promote tumour progression through an ion channel mechanism similar to SLC39A14, which may cooperate with other genes." (PMID 40197818, 2025). "Moreover, SLC39A14 knockdown also facilitated erastin-induced ferroptosis, leading to the suppression of mouse transplantation tumor growth." (PMID 37978473, 2023). "Moreover, SLC39A14 plays an important role in tumor progression by regulating ferroptosis." (PMID 37978473, 2023). "The SLC39A14-PIWIL2 fusion identified in this study follows this mechanism, with the SLC39A14 promoter driving PIWIL2 overexpression, amplifying its tumor-promoting potential in HCC." (PMID 41422314, 2025). "circ_001842 was found to elevate SLC39A14 expression by binding to miR‐502‐5p, consequently resulting in augmented RCC cell proliferation, migration and invasion, as well as EMT in vitro and tumour growth in vivo." (PMID 32729666, 2020). "Interestingly, SLC39A14 expression in HCC samples, including AJHCC007, was lower than in non-tumor samples, while PIWIL2 expression was markedly elevated in AJHCC007." (PMID 41422314, 2025). "In addition, this study establishes the oncogenic role of SLC39A14-PIWIL2 in HCC; however, further investigation is needed to elucidate its role in the tumor microenvironment and its interplay with immune evasion mechanisms." (PMID 41422314, 2025). "In addition, our data suggested that the expression levels of ATP11 C, CSE1L, SLC39A14, SLCO5A1, and GLS were higher in tumor tissues than in normal tissue by a factor of 3.4, 4.7, 2.8, 1.7 and 3.6, respectively." (PMID 34516344, 2021). "Moreover, tumor cells can express ionic iron importers such as divalent metal transporter (DMT)-1 and solute carrier family 39 member 14 (SLC39A14; also known as ZIP14) as well as receptors for FT and transferrin-bound iron (TBI)." (PMID 33842333, 2021).
infection (11 papers, 2014 to 2024). The state of being infected such as from the introduction of a foreign agent such as serum, vaccine, antigenic substance or organism. "Slc39a14, which codes for a divalent metal transporter, is unusual in its substantial up-regulation with infection." (PMID 37318981, 2023). "In this connection, interleukin-6-mediated induction of Zip14/SLC39A14 is known to mediate the uptake of zinc into the liver during acute inflammation and infection, which is believed to be host defensive." (PMID 35058926, 2021).
movement disorder (4 papers, 2017 to 2025). Neurological conditions resulting in abnormal voluntary or involuntary movement, which may impact the speed, fluency, quality and ease of movement. "In contrast, global Slc39a14-knockout mice have dysregulated Mn metabolism and develop behavioral and motor deficits similar to the movement disorder symptoms in patients with an SLC39A14 mutation." (PMID 28751976, 2017).
neurological disease (4 papers, 2016 to 2024). "Individuals with SLC39A14 deficiency do not develop polycythaemia or abnormal iron indices, and liver function is preserved even in cases with advanced neurological disease." (PMID 27231142, 2016).
metabolic disease (3 papers, 2015 to 2024). A congenital disorder (due to inherited enzyme abnormality) or acquired (due to failure of a metabolically important organ) disorder resulting from an abnormal metabolic process. "ZIP14 (SLC39A14) also appears to be closely associated with metabolic diseases." (PMID 39850557, 2024).
SLC39A14 also shares sentences with these, for which no sentence is quoted: Zinc deficiency (11 papers); hemochromatosis (8); endotoxemia (5); Hyperinsulinemia (5); lung carcinoma (5); Obesity (5); iron deficiency (4); pancreatic cancer (4); diabetes (3); Hypoglycemia (3); metabolic syndrome (3); Osteopenia (3); congenital disorder of glycosylation type IIn (2); diabetic nephropathy (2); dwarfism (2); esophageal squamous cell carcinoma (2); heart failure (2); immune dysfunction (2); inflammatory bowel disease (2); Insulin resistance (2); liver cancer (2); Onset (2); prion disease (2); thalassemia (2); acrodermatitis enteropathica (1); acute myeloid leukemia (1); adenoma (1); alcoholic liver diseases (1); asthenozoospermia (1); Ataxia (1).
A further 38 diseases each share a sentence with SLC39A14 in 1 paper.